LGALS3 (galectin 3)
Diseases named in the same sentence as LGALS3 in open-access papers (continued):
Sharing a sentence is not in itself a finding about the gene and the disease.
Insulin resistance (continued). "However, scientific information on the role of galectin-3 in malaria-related insulin resistance in diabetic and non-diabetic adults is limited." (PMID 40802820, 2025). "Other work has shown a vital role for galectin-3 in regulation of insulin receptor responsiveness, and suggests that treatment with ARSB and enhanced binding of galectin-3 with less sulfated C4S may lessen insulin resistance." (PMID 37813168, 2024). "Moreover, galectin-3 and PRG levels were highly correlated, as well as insulin resistance." (PMID 35008499, 2021). "Moreover, galectin-3 levels correlated with fasting plasma glucose (r = 0.787, P < 0.01), 2-hour plasma glucose (r = 0.833, P < 0.01), CRP (r = 0.501, P < 0.01), and homeostasis model assessment of insulin resistance (HOMA-IR) index (r = 0.518, P < 0.01)." (PMID 26770660, 2016). "This interpretation is consistent with the role of galectin-3 in favoring AGE/ALE disposal, as a number of studies in nondiabetic individuals have shown that serum levels of AGEs or of their carbonyl precursors are independent correlates of insulin resistance, as assessed by HOMA-IR index." (PMID 26770660, 2016).
COVID-19 (71 papers, 2020 to 2026). A disease caused by infection with severe acute respiratory syndrome coronavirus 2. "Galectin-3 has been recognized as a biomarker of inflammation and fibrosis in COVID-19, yet its association with echocardiographic indicators of cardiac involvement remains insufficiently understood." (PMID 41909440, 2026). "Our study assesses serum irisin and galectin-3 levels as prognostic biomarkers for mortality risk in severe COVID-19 patients." (PMID 39465409, 2024). "We further aimed to evaluate if there is a correlation between galectin-3 and markers associated with Treg in COVID-19." (PMID 37175392, 2023). "On one hand, we therefore aimed to explore a possible association of galectin-3 with other markers of an increased thrombotic risk in patients with COVID-19." (PMID 37175392, 2023). "Increased galectin-3 in serum was found to be associated with critical illness severity in patients with COVID-19, and the highest concentrations were further associated with the most severe disease progression and ICU mortality." (PMID 37958814, 2023). "In this study, we demonstrated the association of serum galectin-3 concentration with COVID-19 severity." (PMID 37958814, 2023). "Previous results have shown that galectin-3 is upregulated in proliferative T lymphocytes associated with severe COVID-19 and that a subset of pro-fibrogenic macrophages also expresses biomarkers strongly related to galectin-3." (PMID 37958814, 2023). "Associations of higher plasma galectin-3 levels at baseline in COVID-19 patients with worse outcomes were also reported by others." (PMID 37238973, 2023). "Based on the evidence presented here, we recommend clinicians measure galectin-3 levels upon admission to facilitate allocation of appropriate resources in a timely manner to COVID-19 patients at highest risk of severe outcome." (PMID 35115644, 2022). "The aim of our preliminary study was the assessment of the diagnostic utility of serum galectin-3 in patients with COVID-19." (PMID 34439802, 2021). "The analysis of the ROC curves confirmed that serum galectin-3 measured in hospitalized patients with COVID-19 had moderate diagnostic accuracy for COVID-19 pneumonia and high diagnostic accuracy for the need for ICU treatment." (PMID 34439802, 2021). "We have shown that the diagnostic accuracy of serum galectin-3 for severe COVID-19 (pneumonia and the need for ICU admission) is high and comparable with other relevant diagnostic markers." (PMID 34439802, 2021). "Nevertheless, our study showed that serum levels of galectin-3 were increased in severe COVID-19 in association with acute phase reactants, the marker of endothelial injury (sFlt-1), and the markers of tissue damage." (PMID 34439802, 2021). "Galectin-3 is also associated with disease severity, which suggests that it could be a potential treatment target in patients with COVID-19." (PMID 37175392, 2023). "The aim of this study was to evaluate whether galectin-3 is associated with thrombogenicity in COVID-19." (PMID 37175392, 2023). "Interestingly, also galectin-3 has been proposed as a potential COVID-19-severity-associated marker." (PMID 35806317, 2022). "We may hypothesize that these correlations reflect the simultaneous association of galectin-3 and the mentioned markers with COVID-19 severity." (PMID 34439802, 2021). "Given the pleiotropic roles of galectin-3 (gal3), especially those driving inflammatory-associated immune responses, fibrosis and hypoxia we propose the urgent need to decipher a potential pathological role of this lectin in severe cases of COVID-19 patients." (PMID 32973815, 2020). "Combined assessment of galectin-3 and echocardiographic parameters may aid in identifying early myocardial involvement and improving cardiovascular risk stratification in hospitalized COVID-19 patients." (PMID 41909440, 2026).
COVID-19 (continued). "Furthermore, treatments targeting galectin-3 and the mineralocorticoid receptor have been shown to mitigate endothelial inflammation caused by the virus, pointing towards innovative strategies for treating COVID-19-related complications." (PMID 39465409, 2024). "Galectin-3 is increasingly recognized as a potentially important diagnostic or prognostic biomarker for a variety of inflammatory and fibrotic diseases and has been found to be elevated in patients with idiopathic pulmonary fibrosis and more recently in COVID-19 patients." (PMID 35115644, 2022). "This study aimed to assess the relationship between galectin-3 levels and echocardiographic changes of the left ventricle and left atrium in hospitalized patients with COVID-19." (PMID 41909440, 2026). "This study provides preliminary observational data on the serum levels of galectin-3 and sICAM-1 in diabetic patients hospitalized with COVID-19." (PMID 40733621, 2025). "Galectin-3 ≥ 98.16 ng/mL and sICAM-1 ≥ 51.76 ng/mL both showed high sensitivity and specificity in differentiating diabetic COVID-19 patients from healthy individuals." (PMID 40733621, 2025). "Both small molecule inhibitors and monoclonal antibodies targeting Galectin-3 have potential for antiviral therapy as inhibition by a Galectin-3 antagonist resulted in reduced viral load in COVID-19 patients." (PMID 41036542, 2025). "The serum levels of galectin-3 and sICAM-1 were significantly greater in the diabetic COVID-19 group than in the healthy control group (p < 0.001 for both)." (PMID 40733621, 2025). "Compared with those in the control group, the serum levels of both galectin-3 and sICAM-1 were significantly elevated in patients with COVID-19 and T2D (p < 0.001)." (PMID 40733621, 2025). "Another study examining Galectin-3 in COVID-19 patients identified in-hospital mortality and/or the requirement for invasive mechanical ventilation in severe COVID-19 cases as severe outcomes." (PMID 38674175, 2024). "Galectin 3 (Gal-3) is the most studied galectin in terms of involvement in COVID-19 pathophysiology, complications, and treatment." (PMID 38540252, 2024). "Galectin-3 showed a stronger correlation with mortality outcomes in severe COVID-19 patients compared to traditional clinical and laboratory markers." (PMID 39465409, 2024). "Our study confirms galectin-3 (Gal-3) as a crucial biomarker for predicting severe outcomes in COVID-19, including increased mortality and the development of severe acute respiratory distress syndrome (ARDS)." (PMID 39465409, 2024). "Other studies also reported that significant amounts of galectin-3 are released from inflammatory cells in patients with severe COVID-19 and that increased galectin-3 serum levels correlate with disease severity." (PMID 38674175, 2024). "Multivariate logistic regression confirmed galectin-3 as an independent predictor of mortality in severe COVID-19 cases, with each unit increase in serum level significantly associated with an increased risk of mortality risk (p = 0.037)." (PMID 39465409, 2024). "This study aimed to evaluate the roles of galectin-3 and irisin as biomarkers in predicting severe outcomes in COVID-19 patients." (PMID 39465409, 2024). "This differential expression highlights galectin-3’s potential role in predicting severe outcomes in COVID-19 cases." (PMID 39465409, 2024). "We analyzed serum levels of galectin-3 and irisin in 59 patients with severe COVID-19 and 30 healthy controls." (PMID 39465409, 2024). "The significant role of galectin-3 in COVID-19 pathophysiology highlights its utility as a biomarker and therapeutic target." (PMID 39465409, 2024). "Our findings are consistent with previous studies, which have also described galectin-3 as a possible prognostic and severity marker in COVID-19." (PMID 37175392, 2023). "Galectin-3 serum admission levels were found to negatively correlate with the survival of COVID-19 patients in the ICU." (PMID 37958814, 2023).
COVID-19 (continued). "More specifically, galectin-3 was quantified in the serum of COVID-19 patients hospitalized at the Patras University Hospital." (PMID 37958814, 2023). "In line with this, stratification of 280 COVID-19 patients for disease severity (mild, moderate, severe, and critical) showed a consistent rise of circulating galectin-3 levels from a mild to a critical state." (PMID 37238973, 2023). "Galectin-3 is a potential biomarker for predicting COVID-19 severity, prognosis, and treatment response." (PMID 37298569, 2023). "Single-cell analysis found elevated levels of galectin-3 in monocytes, macrophages, and dendritic cells of patients with severe COVID-19 as compared to mild cases." (PMID 37238973, 2023). "Forthcoming studies focusing on the link between galectin-3 and long COVID-19 will further establish its role in the pathophysiology of this disease." (PMID 37958814, 2023). "This is consistent with observations from the DEFINE Trial, in which COVID-19 patients were treated with an inhaled galectin-3 inhibitor." (PMID 37175392, 2023). "Previous studies addressing the role of galectin-3 in COVID-19 have focused on diagnosing COVID-19 pneumonia or the need for mechanical ventilation." (PMID 37958814, 2023). "Galectin-3 is involved in various aspects of COVID-19 pathogenesis, including promotion of inflammation, dysregulation of immune response, fibrosis and tissue remodeling, and endothelial dysfunction and thrombosis." (PMID 37298569, 2023). "A significant increase in galectin-3 levels and admission levels in critically ill COVID-19 patients compared to patients with moderate disease was shown." (PMID 37958814, 2023). "Previous studies have reported that galectin-3 upregulation can serve as a prognostic biomarker in COVID-19 patients, but its role in the disease process was not entirely clear." (PMID 37628961, 2023). "The aim of this study was to evaluate the relationship between galectin-3 and the clinical severity of COVID-19, as well as assess the prognostic accuracy of galectin-3 for the probability of ICU mortality." (PMID 37958814, 2023). "Here the authors observed that the inhibitor lowered the D-dimer level in comparison to that of the controls, which further suggests that galectin-3 inhibition can influence coagulopathy in COVID-19 patients." (PMID 37175392, 2023). "Correlation analysis between galectin-3 and COVID-19 biomarkers showed a significant correlation with the serum levels of D-dimers, LDH, ferritin and CRP." (PMID 37958814, 2023). "High galectin-3 levels in patients with severe COVID-19 led Gaughan and coworkers to propose the pharmacological galectin-3 inhibitor GB0139 as a potential therapeutic approach in COVID-19-related pneumonitis." (PMID 37238973, 2023). "Increased serum levels of galectin-3 (>30 ng/mL) have been correlated with severe COVID-19 outcomes." (PMID 37064248, 2023). "Due to the involvement of galectin-3 in inflammatory processes, recent studies have also examined galectin-3 as a biomarker of severity of COVID-19." (PMID 37568870, 2023). "This prospective case–control study included 100 patients, and lower serum galectin-3 levels were measured in severe/critical COVID-19 patients compared to the moderate disease group and healthy controls." (PMID 37238973, 2023). "Although the relationship between galectin-3 and COVID-19 has been studied before, in this study we mainly aimed to explore its correlation with worse outcomes and increased mortality in the ICU." (PMID 37958814, 2023). "Our single-cell transcriptome analysis revealed that epithelial galectin-3 and receptor interactions were associated with the impaired mitochondrial function and cell cycle arrest of CD8+ T cells in severe/critical COVID-19." (PMID 37628961, 2023). "In order to investigate the prognostic utility of galectin-3 in critical COVID-19, we then focused on the patient group hospitalized in the ICU, which was further divided in survivors and non-survivors." (PMID 37958814, 2023).
COVID-19 (continued). "In the present study, we assessed galectin-3 levels, as well as distinct coagulation and immune reaction markers, in a cohort of COVID-19 patients and compared them with a cohort of patients with acute respiratory diseases other than COVID-19." (PMID 37175392, 2023). "Our results showed that median galectin-3 serum levels on admission were significantly increased in critical COVID-19 patients (7.2 ng/mL), as compared to the median levels of patients with less severe disease (2.9 ng/mL, p = 0.003)." (PMID 37958814, 2023). "The link between galectin-3 and clinical severity, as observed in our cohort, in both COVpos and COVneg patients supports findings from previous studies on COVID-19." (PMID 37175392, 2023). "Most relevant for the COVID-19 disease progression, galectin-3 is also known to often worsen viral infectious diseases." (PMID 37238973, 2023). "Targeting Galectin-3 has been suggested as treatment for COVID-19 not only due to its role in fibrosis and systemic inflammation, but also due to its potential involvement in the virus-host interaction mediated by the N-terminal domain of SARS-CoV-235,36." (PMID 35115644, 2022). "The present study aims at investigating the potential usefulness of bradykinin and galectin-3 levels, obtained at hospital admission, as predictors of COVID-19 progression into severe or deadly forms of the disease." (PMID 36338343, 2022). "Higher levels of galectin-3 among COVID-19 patients were also reported in a rather small Taiwanese study." (PMID 35326373, 2022). "Using ROC analysis, a larger area under the curve (AUC) for the serum Galectin-3 level of the control group (AUC=0.622, 95% CI = 0.529-0.714; p=0.015) was calculated compared to the COVID-19 patient group for the diagnosis of COVID-19 disease." (PMID 36225452, 2022). "Galectin-3 significantly correlated with several inflammatory and thrombo-inflammatory biomarkers, indicating its pathophysiological implication in COVID-19’s inflammatory response." (PMID 35115644, 2022). "We found that COVID-19 patients upon hospital admission had significantly elevated circulating levels of galectin-3 when compared to age-matched pre-pandemic healthy subjects (28.77 ng/mL [17.52–42.04] vs. 9.65 ng/mL [8.27–14.71], p < 0.0001)." (PMID 35115644, 2022). "The results imply that levels of Gal-1 and Galectin-3 (Gal-3) are elevated in COVID-19 patients in comparison to healthy patients." (PMID 35075140, 2022). "Using ROC analysis, a larger area under the curve (AUC) for the serum Galectin-3 levels of the control group (AUC=0.622, 95% CI =0.529-0.714; p=0.015) was calculated compared to the COVID-19 patient group for the diagnosis of COVID-19 disease." (PMID 36225452, 2022). "This study presents for the first time an important connection between galectin-3 and the hyperinflammatory state in COVID-19 patients." (PMID 35115644, 2022). "Elevated concentrations of C5a, Galectin-3, ICAM-1 and VCAM-1 on presentation were associated with the composite outcome of ICU- admission or 30-day mortality in COVID-19 and controls, yet more pronounced in COVID-19." (PMID 36203596, 2022). "The correlation analysis among all COVID-19 patients confirmed the statistically significant correlation between some markers of oxidative stress and cytokine bradykinin and peptide galectin-3." (PMID 36338343, 2022). "Galectin-3 has been studied recently in an Italian cohort of hospitalized COVID-19 patients with acute respiratory failure (n = 156)." (PMID 35326373, 2022). "Previous studies showed increased Galectin-3 plasma levels in patients with COVID-19 compared to healthy controls." (PMID 36203596, 2022). "C5a levels correlated moderately with markers of endothelial cell activation and Galectin-3 in both, COVID-19 cases and controls, whereas the correlation was weaker for sC5b-9." (PMID 36203596, 2022).